ASCL1 (achaete-scute family bHLH transcription factor 1)
Diseases named in the same sentence as ASCL1 in open-access papers (continued):
Sharing a sentence is not in itself a finding about the gene and the disease.
cancer (98 papers, 2008 to 2025). A tumor composed of atypical neoplastic, often pleomorphic cells that invade other tissues. "Both Pearson and Spearman correlation analyses demonstrated a strong association between ASCL1 and immunomodulatory factors in pan-cancer contexts." (PMID 39963143, 2025). "Subsequent research has increasingly linked ASCL1 overexpression to oncogenic activity in various cancers, with significant associations with poor prognosis and therapeutic resistance." (PMID 39963143, 2025). "From this panel, we have arbitrarily selected 2 representative genes, ZIK1 and ASCL1 (previously identified as being differentially methylated in HPV-associated cancers), for expanded analyses." (PMID 34882728, 2021). "Indeed, only neuronal stem cells (Nestin+ or GFAP+ cells) and early progenitors (Ascl1+ or NG2+ cells) that are at the top of the differentiation hierarchy are susceptible to cancer formation, while tumorigenesis is abolished in immature or post-mitotic neurons (NeuroD1+ or CamKIIα+ cells)." (PMID 35706426, 2022). "Further studies are required to elucidate the regulatory mechanisms underlying the mutual repression of ASCL1 and NEUROD1 along with the direct NEUROD1-mediated repression of BCL2 across different types of cancer and disease." (PMID 40082639, 2025). "Regulation of ASCL1 by phosphorylation has important implications for understanding its role in cancer, in which cells often have a hyperactive kinase environment." (PMID 40527452, 2025). "By addressing these outstanding questions, we can better harness the potential of ASCL1 for therapeutic applications in neurological disorders, regeneration and cancer." (PMID 40527452, 2025). "By integrating these perspectives, this review provides a comprehensive overview of the diverse roles of ASCL1 in development, reprogramming and cancer, offering insights into its molecular functions and therapeutic potential." (PMID 40527452, 2025). "The mRNA expression of ASCL1 was analyzed across multiple cancer types using combined data from the TCGA and GTEx databases, addressing the lack of normal individual data in TCGA." (PMID 39963143, 2025). "In particular, a combination of methylation markers ZNF582 and ASCL1 shows the highest accuracy for AIN3+ detection and provides a promising tool to identify HSIL at risk of progression to cancer and in need of treatment." (PMID 40400293, 2025). "More recent evidence suggests ASCL1 TF activity is functionally required for neuroendocrine reprogramming of cancer cells." (PMID 40994652, 2024). "Guided by the HTAN-SCLC cancer epithelium dataset, we further found that the RNA expression of ASCL1, PHOX2A and AR was regulated by ZNF536." (PMID 38720348, 2024). "DPYSL5 overexpression also led to increased mRNA expression of Nanog, SOX2, NSE, CGA, and ASCL1, suggesting that cells achieve characteristic of neuron-like cancer progenitor cells, possibly through the activation of EZH2." (PMID 38238517, 2024). "To determine the cancer type composition of the PGC-1α/ASCL1-High subpopulation compared to the rest of the samples, we quantified the percentage of cell lines with SCN features in both groups." (PMID 39589879, 2024). "For example, in cancer cells, unphosphorylated ASCL1 can increase neuronal differentiation and contribute to reducing tumorigenesis by forcing cells to exit the cell cycle." (PMID 39575884, 2024). "The basic helix-loop-helix (bHLH) family of transcription factors, which includes the ASCL1 gene, has been the subject of much research due to its diverse function in cancer biology and developmental processes." (PMID 38780447, 2024). "These mutations represent additional insight into how genes such as IGF1R, MSI2, MBD2, and ASCL1 can be aberrantly regulated in cancer, highlighting the importance of expanding the field’s view of cancer genomics to include alterations in UTRs." (PMID 37516102, 2023).
cancer (continued). "The talazoparib IC50 value was markedly increased in pan-cancer samples that had ASCL1 copy number deletion (two-way ANOVA P = 1.89e−4)." (PMID 35739271, 2022). "Exploiting the transcriptional dependency of cancer cells (here mainly directed by two well‐known DNA‐binding proteins: ASCL1 and NEUROD1) as an Achilles’s heel to thwart their own tumorigenic potential, represents a key actionable mechanism against SCLC." (PMID 35263037, 2022). "HSP prevented BON cancer cell proliferation and induced cancer cell death by decreasing achaete-scute complex-like 1(ASCL1), chromogranin A (CgA), and enhanced Notch 1 expression." (PMID 35128104, 2022). "ASCL1 has been described as having both a growth promoting and growth suppressing role in human cancers." (PMID 36263020, 2022). "Understanding genome-wide responses to changes in ASCL1 levels and phosphorylation status has significant implications for its use in approaches to direct cell fate and manipulation of its function in cancer cells and reprogramming protocols." (PMID 35366798, 2022). "ChIP-seq data on human cancer cell lines comparing ASCL1 and NEUROD1 transcriptional targets demonstrates that these two bHLH genes bind to distinct genomic regions." (PMID 34782629, 2021). "These downstream targets of ASCL1 are “druggable” by drugs either approved in other cancer types or in clinical trials." (PMID 33191657, 2021). "The genes assayed were neuroendocrine-associated genes (INSM1, ASCL1, NRCAM, and SNAP25), one gene centered in the gene regulatory network (NUF2), and five possibly cancer-associated genes (PTP4A3, RFC4, REST, APEH, and FBLN2)." (PMID 34395507, 2021). "IHC revealed that the expression of TTF‐1 and ASCL1 showed positive correlation in the nucleus of cancer cells." (PMID 31782890, 2020). "Taken together, these findings suggest that ASCL1 is a transcriptional regulator at the epicenter of multiple biological processes that are fundamental to cancer development." (PMID 32573857, 2020). "At 12 weeks, progenitor GSCs gave rise to tumors expressing mainly the progenitor marker ASCL1 and small populations of cancer cells expressing the neuronal marker DCX or the astro-mesenchymal marker CD44." (PMID 32641768, 2020). "In these contexts, phosphorylation of ASCL1 restrains its ability to promote differentiation, an effect analogous to that described for other proneural bHLHs in development and cancer." (PMID 29759978, 2018). "In the preceding paragraphs, the possibility of forced expression of Ascl1 as a potential therapeutic approach for brain injury and cancer is considered." (PMID 28832532, 2017). "JQ1 is known to induce growth suppression by transcriptional inhibition of numerous genes, including MYC, MYCN and ASCL1, in human cancer cells." (PMID 27764802, 2016). "ASCL1 was significantly decreased in cancer compared to control by 0.32-fold, p = 0.003 (RT-PCR) vs. 0.36-fold p = 0.0001 (Affymetrix microarray)." (PMID 25705890, 2015). "The mechanism by which the Notch-RBPJk pathway represses Ascl1 expression can be inferred from studies in the embryonic brain and in cancer cells, which have shown that the Notch-induced Hes factors directly repress the Ascl1 gene." (PMID 25189209, 2014). "ASCL1 expression was significantly elevated in various cancer tissues, including BC." (PMID 39963143, 2025). "Thus, ASCL1 plays multifaceted roles in development, fate reprogramming and cancer via mechanisms that go beyond activating transcription." (PMID 40527452, 2025). "We additionally draw attention to the BAF chromatin remodeler BCL7A, for which we found no ASCL1 connection in the literature, and which is also associated with diverse cancers." (PMID 40257984, 2025). "Thus, four distinct subtypes of SCLC defined by the predominant transcriptional regulatory mechanism operating in cancer cells have been described on the basis of the expression of ASCL1, NEUROD1, YAP1, and POU2F346." (PMID 41290592, 2025).
cancer (continued). "In cancer, these TFs act as activators (ASCL1) or inhibitors of the cell cycle progression (E2A)." (PMID 38711090, 2024). "Notably, the NPC/GPC-like cancer cells are marked by ASCL1 or its direct target genes (DLL3, HES5) and are resistant to TMZ treatment." (PMID 39609428, 2024). "•Elevated ASCL1 and ZNF582 methylation is associated with progression to cancer." (PMID 38160718, 2023). "These genes serve as markers of proliferation and appear to be controlled by ASCL1 in cancer cells." (PMID 37958729, 2023). "In addition to its role in neurogenesis and cancer, ASCL1 has emerged as a key component in transcription factor cocktails that can be used to reprogramme a variety of cells into neurons." (PMID 35366798, 2022). "Subsequently, we validated the most potent markers (ASCL1, LHX8, SST, WDR17, ZIC1 and ZNF582) in a large independent series, confirmed the accuracy (AUC = 0.89) and showed that high methylation levels are associated with progression towards cancer." (PMID 33580586, 2021). "Here, we explore some of the top ranked TRs including histone deacetylase 2 (HDAC2), estrogen receptor 1 (ESR1), TEA domain family member 4 (TEAD4), achaete-scute homolog 1 (ASCL1), androgen receptor (AR) and yes associated protein 1 (YAP1) in several cancer types." (PMID 33778495, 2021). "In support of these experimental findings, in silico Pearson correlation analysis of human GBM specimens by R2 indicated that NDRG1 expression was anti-correlated to that of ASCL1 in the majority of GBM samples as well as in other different types of cancer (TCGA and PANCANCER datasets)." (PMID 30538287, 2019). "Although a good number of caveats exist, exogenous over-expression of Ascl1, alone or in combination with other factors, may be worth further consideration as a therapeutic approach in brain injury and cancer." (PMID 28832532, 2017). "In SCLC, previous studies indicated that JQ1 targeted MYCL and ASCL1 to inhibit cancer cell growth." (PMID 29156797, 2017). "Conversely, Ascl1 may adversely impact chemotherapy during cancer treatment by contributing to the development of chemoreristancce which commonly happens in SCLCs." (PMID 23300791, 2012). "It has been advocated that ASCL1 expression may favour cancer cell growth through repression of DKK1 with the consequential aberrant activation of the Wnt/β-catenin signalling pathway." (PMID 19744316, 2009). "HEPACAM2 is another gene implicated in cancer that we could not find a direct ASCL1 association in the literature." (PMID 40257984, 2025). "All these results imply that ASCL1 may play a cancer-promoting role in BC." (PMID 39963143, 2025). "Moreover, several TFs play known roles in cancers, such as ASCL1, NCOR1, SMAD2, and SMAD4." (PMID 39716176, 2024). "Pioneer transcription factors (such as ASCL1 or OTX2) capable of reprogramming cancer cells may identify novel transcriptional and proteomic profiles that could be targeted to inhibit complete transdifferentiation into a pure small cell/neuroendocrine lineage state." (PMID 39349591, 2024). "Therefore, the interplay between Myc family members, ASCL1, Notch signaling, and other factors in regulating NE plasticity in cancer may be reflecting their roles in driving cell fate toward NE or non-NE lineage during normal tissue development." (PMID 37255415, 2023). "Interestingly, the ASCL1 role is evolutionarily conserved; in fact, ASCL1 overexpression efficiently reduces growth capacity of proneural human cancer stem cells-derived models of GBM and promotes a lineage switch, activating the neuronal fate and repressing the glial one." (PMID 35706426, 2022). "Compared to primary cancer samples, genes such as GLYATL2, EDIL3, MEG3, FABP4, ASCL1, GRP, and WDFY4 were highly upregulated in CRPC, with statistically significant differences underscoring their potential roles in driving the castration-resistant phenotype." (PMID 40165961, 2025).
cancer (continued). "Here, via multiomics analyses of 314 SCLCs, we found that the ASCL1+/MKI67+ and ASCL1+/CRIP2+ clusters accounted for 74.38% of the 190,313 SCLC cancer cells from 39 patients, with the ASCL1+SOX1+ stem-like cell cluster across SCLC subtypes." (PMID 40925909, 2025). "Stabilization of ASCL1 levels via treatment with Notch inhibitor, DAPT, has been shown to promote neurogenesis both in human neural stem cells and in cancer cells." (PMID 40527452, 2025). "We conducted a coexpression analysis of PGC-1α against the four SCNC lineage markers—ASCL1, POU2F3, NEUROD1, and YAP1—across all 1,466 human cancer cell lines from the Cancer Cell Line Encyclopedia (CCLE)." (PMID 39589879, 2024). "It is worth noting that the stable ASCL1 protein activates CD47 transcription and enhances cancer cell characteristics." (PMID 37783914, 2023). "First, we downloaded the bulk expression data for 50 SCLC cell lines from the Cancer Cell Line Encyclopedia (CCLE) and categorized them according to the key TFs ASCL1, NEUROD1, POU2F3 and YAP1." (PMID 36195615, 2022). "The optimal marker panel (ASCL1 and ZIC1; AUC = 0.85 for AIN3+) detected 98% of cancers at 79% specificity." (PMID 33580586, 2021). "Pathways related to nervous system development (FDR = 5.8 × 10−8) were enriched for the PID-N genes ASCL1, CTNNB1, ID2, SUFU, and TERT that have known roles in cancer, complementing the PID-C genes NOTCH1, PTEN, and RHOA that also have known cancer roles." (PMID 32024854, 2020). "For example, ASCL1, CDX2, IRF4, MITF, NKX2-1, PAX8 and SOX2 were pinpointed as outliers in cell lines of their corresponding cancer tissue origins." (PMID 31050342, 2019). "On the other hand, ASCL1 and ST6GALNAC5 have been described as protumorigenic in other cancer types." (PMID 30360578, 2018). "Based on in situ immunostaining patterns for achaete-scute homolog 1 (ASCL1) and NEUROD1, it is proposed that c-Myc-driven cancer cells emerge among ASCL1-positive precursor cells, and these early-staged cancer cells initially exhibit classic morphology." (PMID 30477547, 2018). "Based on in situ immunostaining patterns for achaete-scute homolog 1 (ASCL1) and NEUROD1, it is proposed that N-Myc-driven cancer cells emerge among ASCL1-positive precursor cells, and these early-staged cancer cells initially exhibit classic morphology." (PMID 30053872, 2018). "Western blot analysis revealed that treatment of NE cancer cells with TDP-A changed the NE phenotype in all three cell lines and led to dose-dependent decrease in the expression of ASCL1, SYN and CgA." (PMID 29050323, 2017). "In addition to subtype markers (ASCL1, NEUROD1, POU2F3, and YAP1), the expression of nine cancer-specific proteins was evaluated." (PMID 40107154, 2025). "constructs a novel model of SCLC subtypes defined by differential expression of four key transcription regulators: ASCL1, NeuroD1, YAP1, and POU2F3 according to SCLC primary human tumors, patient-derived xenografts, cancer cell lines, and genetically engineered mouse models." (PMID 40433367, 2025). "To determine whether PGC-1α/ASCL1-High cells show increased SCN differentiation, we applied a well-established SCN score derived from a pan-cancer transcriptomic analysis." (PMID 39589879, 2024). "The TF ASCL1 plays a direct role in maintenance of CBC cells in intestinal crypts during normal homeostasis and is also important for neuroendocrine lineage reprogramming in several cancer types." (PMID 40994652, 2024). "Developmentally, GBM cells follow a roadmap similar to that of the fetal brain, where ASCL1 marks the presence of highly proliferative, TMZ-resistant glial progenitor (GPC) cancer cells at the apex of astroglial, oligodendroglial, neuronal, and mesenchymal cancer cells." (PMID 39609428, 2024). "ASCL1 KO tumors developed a poorly differentiated carcinoma without detectable expression of the NE lineage markers SYP, INSM1, or DLL3 but showed higher expression of NOTCH2, HES1, and KRT8." (PMID 39024561, 2024).
cancer (continued). "Among the NE markers, synaptophysin was variably positive in two NUT carcinomas (2/6, 33%); however, all cases were negative for ASCL1, chromogranin A, and CD56." (PMID 38326851, 2024). "Consistent with the inference, we observed longer overall survival of patients with higher expression of ASCL1 although we did not detect differences in RNA levels between normal and cancer cells." (PMID 35165277, 2022). "One notable finding was enrichment of the DNA binding motif for ASCL1, which we previously identified as upregulated in H3.3K27M DIPG cells and important for their cancer-related cellular functions, in both XIII and XVII cells compared to their isogenic wild-type counterparts." (PMID 35590427, 2022). "Finally, the very small tumors stemming from astro-mesenchymal GSCs expressed mainly ASCL1 and a small population of CD44-expressing cancer cells." (PMID 32641768, 2020). "An understanding of ASCL1's role in regulating the proliferation of NG2‐glia may therefore provide new insights into the formation and progression of these cancers." (PMID 29683222, 2018). "Amiloride has been shown to decrease the proliferation of neuroendocrine lung cancer cells which highly express ASCL1 but not in cancer cells with low ASCL1 expression." (PMID 30053872, 2018). "Furthermore, analysis of the HTAN-SCLC dataset showed that ZNF536 was primarily expressed in the cancer epithelium and not in the ASCL1+ subpopulation." (PMID 38720348, 2024). "In line, Gene Ontology and KEGG pathway analysis of ASCL1‐target genes and NEUROD1‐target genes in our RNA‐seq dataset showed that ASCL1 and NEUROD1 are involved in DNA metabolic process mainly devoted to RNAPII transcription regulation and cancer‐related pathways (Fig EV4A and B)." (PMID 35263037, 2022). "However, the molecular fundaments of ASCL1- and NEUROD1-regulated subtypes in both cancers remain largely unknown." (PMID 34145257, 2021). "However, since ASCL1 shows strong preferences in binding to canonical E‐box (CANNTG) motifs in the genome of highly proliferative neural progenitors and cancer cells, it is likely that E47 may also be a dimerization partner in NG2‐glia." (PMID 29683222, 2018).